PER1 (period circadian regulator 1)
Diseases named in the same sentence as PER1 in open-access papers (continued):
Sharing a sentence is not in itself a finding about the gene and the disease.
lung carcinoma (13 papers, 2016 to 2025). "To further explore the association between LKB1 and PER1 in lung cancer we used publicly available human lung cancer datasets to investigate how STK11 mutation status related to PER1 expression in lung adenocarcinoma." (PMID 40715535, 2025). "High PER1 expression in lung cancer patients correlates with LKB1 mutation status, decreased expression of the gene that encodes PD-L1, and altered hypoxia and immune and stromal ESTIMATE scores." (PMID 40715535, 2025). "Knockdown of PER1 decreases cell growth, proliferation, and invasion in LKB1-deficient models, which suggests that PER1 has an oncogenic role in STK11-mutant lung cancer." (PMID 40715535, 2025). "Having established that knockdown of PER1 has functional impacts on the proliferation and invasion of lung cancer cells, we next investigated how PER1 mRNA and PER1 protein expression levels relate to mutation status in the TCGA LUAD and 2020 CPTAC datasets, respectively." (PMID 40715535, 2025). "Generally, when data is analyzed without consideration of specific driver mutations or molecular subtype, PERs have been shown to possess tumor suppressor activity in a variety of cancers, with low PER1 expression associated with poorer prognosis in lung cancer patients taken as whole." (PMID 40715535, 2025). "Various molecular pathways and genes such as BMAL1, SIRT1, HLF, and PER1 and their implications in aging, circadian rhythms, and lung cancer will also be discussed." (PMID 39812541, 2025). "We also sought to determine the impact of PER1 knockdown in the STK11-mutant A549 human lung cancer cell line." (PMID 40715535, 2025). "Because the main driver for lung cancer mortality is metastasis, we used invasive ‘leader’ and non-invasive ‘follower’ cells from the parental H1299 cell line to investigate the role of PER1 in lung cancer collective cell invasion." (PMID 40715535, 2025). "Addback of wildtype LKB1 in A549 lung cancer cells is sufficient to decrease PER1 protein levels." (PMID 40715535, 2025). "The objective of this study was to investigate PER1 mRNA expression and PER1 protein expression in LKB1-deficient cell models and lung cancer patient samples and to assess the functional impact and clinical significance of high PER1 and PER1 expression in LKB1-deficient lung cancer." (PMID 40715535, 2025). "In addressing the first question, research should establish the molecular mechanism connecting LKB1 to the regulation of PER1 expression and establish whether the role of PER1 in LKB1-deficient lung cancer is clock-dependent." (PMID 40715535, 2025). "This study suggests that PER1 may be a context specific oncogene in LKB1-deficient human lung cancer, underscoring the importance of considering mutational context in studies of lung cancer and chronotherapy." (PMID 40715535, 2025). "PER1 has oncogenic activity in LKB1-mutant lung cancer cells and high PER1 expression in lung adenocarcinoma patients may represent an independent biomarker of resistance to immunotherapy." (PMID 40715535, 2025). "Moreover, lower mRNA of PER1, PER2 and PER3 are linked to poor overall survival rates in lung cancer patients, indicating that these genes are prognostic markers." (PMID 34162762, 2021). "Thus, PER1 may have unique subtype-specific roles in lung cancer with critical implications for treatment efficacy." (PMID 40715535, 2025). "Collectively, lung cancer patients with high expression of TIMELESS or low expression of RORA, PER1, PER2, or CRY2 had a significantly poorer prognosis in OS." (PMID 35078435, 2022).
lung carcinoma (continued). "Furthermore, in A549 lung cancer cells, which are STK11-mutant, addback of wildtype LKB1 was sufficient to reduce PER1 levels." (PMID 40715535, 2025). "Furthermore, we used the CCLE to analyze mRNA expression levels of PER1, PER2, PER3, CRY1, and CRY2 in lung cancer cell lines in current lung cancer research." (PMID 36385012, 2022). "Functionally, we could show that PER1 reduced the sensitivity of cancer cells to drug-induced apoptosis, both in vitro and in vivo in NOD scid gamma (NSG) mice xenotransplanted with a lung cancer cell line." (PMID 33804124, 2021).
oral squamous cell carcinoma (12 papers, 2013 to 2025). "Low expression of PER1 is associated with poor prognosis in patients, and PER1 may be an important therapeutic target for oral squamous cell carcinoma." (PMID 34220965, 2021). "A recent review discusses the association of the circadian clock gene PER1 with oral cancer pathogenesis and suggested that changes in its expression may play an important role in the initiation and progression of oral squamous cell carcinoma." (PMID 31040792, 2019). "Per1, a negative regulator of Bmal-1, has been demonstrated to promote ferroptosis in the experiments of oral squamous cell carcinoma, which shows that Bmal-1 functions as a ferroptosis prohibitor." (PMID 39296207, 2024). "PER1 promotes the progression of oral squamous cell carcinoma by inhibiting autophagy-mediated apoptosis and enhancing cell proliferation in an Akt/mTOR-pathway-dependent manner." (PMID 34220965, 2021). "In this study, we used short hairpin RNA interference to knock down PER1 effectively in SCC15 human oral squamous cell carcinoma cells." (PMID 27602964, 2016). "Here, we designed short hairpin RNAs (shRNAs) to effectively knock down PER1 in SCC15 human oral squamous cell carcinoma cells." (PMID 26943040, 2016). "We previously demonstrated that mRNA and protein expression of PER1 are remarkably reduced in oral squamous cell carcinoma (OSCC) compared to para-carcinoma tissue." (PMID 27602964, 2016). "Here, we discovered that PER1 was markedly downregulated in oral squamous cell carcinoma (OSCC)." (PMID 33723221, 2021). "Therefore, PER1 played a significant part in the occurrence and development of oral squamous cell carcinoma." (PMID 23405233, 2013). "The results of PER1 expression in BSCC and its correlations with patients' clinical pathologic parameters indicated that PER1 expression might be used to evaluate the stage and metastatic risk of patients with oral squamous cell carcinoma." (PMID 23405233, 2013). "For instance, the tumor suppressor gene PER1 inhibits glycolysis-mediated cell proliferation by regulating PI3K stability and PI3K/AKT pathway dependence, thereby inhibiting oral squamous cell carcinoma progression." (PMID 38778403, 2024). "The downregulation of period circadian regulator 1 (PER1) gene expression has been found to enhance tumorigenicity and proliferation of oral squamous cell carcinoma cells." (PMID 34976055, 2021). "In oral squamous cell carcinoma (OSCC), PER1 inhibits glycolysis-mediated cell proliferation by forming a PER1/receptor for activated C kinase 1 (RACK1)/phosphatidylinositol 3-kinase (PI3K) complex, regulating PI3K stability, and modulating PI3K/protein kinase B (AKT) signaling-dependent mechanisms." (PMID 41451215, 2025).
Hypertension (11 papers, 2013 to 2025). The presence of chronic increased pressure in the systemic arterial system. "Deletion of Per1 in hypertensive male mice resulted in lower blood pressure as compared to wild-type mice, suggesting that loss of Per1 was protective in the setting of hypertension." (PMID 37298261, 2023). "Bhlhe41 was shown to modulate hypertension susceptibility, Per1 was found to play a role in regulating blood pressure, Dbp functions in cardiac hypertrophy, ventricular function, and contractility, while Bhlhe40 functions in cardiac morphogenesis and development." (PMID 24255707, 2013). "Emerging evidence suggested that clock genes such as Baml, Ck1e, Cry1, Per1 and Per2 play an integral role in the development of hypertension and kidney disease." (PMID 28368364, 2017). "This suggests that PER1 may be involved in the progression of hypertension by regulating the renin-angiotensin-aldosterone system (RAAS)." (PMID 41451215, 2025). "In contrast, gene expression profiling of Spontaneously Hypertensive (SHR) rats, a genetic model of hypertension, demonstrated decreased expression of Bmal1 and Npas2, while Per1, Per2, Per3, Cry1, Cry2, Bhlhe41 and Csnk1D were all upregulated compared to naïve WKY controls." (PMID 33127986, 2020). "In addition, in hypertension models, PER1 and the orexin system genes exhibit coordinated regulation of expression, which may influence the pathogenesis of sleep apnea syndrome." (PMID 41451215, 2025). "Moreover, in contrast to C57BL/6 background, male Per1 KO mice on a 129/sv background in combination with HS/DOCP challenge are extraordinarily protective from hypertension, implying that sexual hormones might be fundamental to Per1 medicated circadian BP control." (PMID 34207942, 2021). "Mice lacking the Per1 gene exhibit altered circadian rhythm and impaired heart function, with an increased likelihood of hypertension and kidney injury when on a sodium-rich diet." (PMID 40943656, 2025). "High salt diet plus mineralocorticoid deoxycorticosterone pivalate (HS/DOCP) injection significantly resulted in non-dipping hypertension and renal sodium handling defect (<10% difference between active and inactive phase) in male Per1 knockout mice." (PMID 34207942, 2021). "PER1 knock-out female mice have a steady drop in blood pressure overnight and are protected from hypertension without dipping." (PMID 34066863, 2021). "Interestingly, the female Per1 knockout mice appeared to be protective against non-dipping hypertension in response to HS/DOCP treatment in sex-dependent manner to some extent." (PMID 34207942, 2021). "Deletion of Per1 in 129/SV mice led to a significantly lower BP compared with control mice; however, loss of Per1 in male C57BL/6 mice resulted in an increase in BP observed only during the active phase, and exhibited nondipping hypertension following high salt plus mineralocorticoid treatment." (PMID 33415319, 2021).
breast tumors (9 papers, 2010 to 2025). "Both sporadic and familial breast tumors have decreased expression levels of PER1 and PER2 when compared to normal breast tissue." (PMID 33089179, 2019). "A previous study has shown that the rhythmic patterns of Per1 and Per2 mRNA expression disappeared in tumor cells of breast tumor bearing mice." (PMID 26337663, 2015). "It has also been shown that PER1 expression decreases significantly in breast tumors." (PMID 33194597, 2020). "The familial tumors had significantly decreased levels of PER1 even when compared to sporadic breast tumors, suggesting that aberrant clock gene expression may be important in the development of familial breast cancer." (PMID 33089179, 2019). "Significantly decreased expression of Per1 has been observed between sporadic breast tumors and normal samples, as well as a further significant decrease between familial and sporadic breast tumors for both Per1 and Per2 suggesting a role for both in normal breast function." (PMID 20353609, 2010). "One study suggested that decreased expression of PER1 and PER2 in breast tumors was due to the methylation of the PER gene promoters." (PMID 33089179, 2019). "A significant decrease in PER1 and PER2 expression has been demonstrated in sporadic and familial primary breast tumours when compared to normal breast tissue." (PMID 30348208, 2018). "We found significantly decreased expression of CRY2, PER1, PER2 genes in the ER/PR negative breast tumors compared to the ER/PR positive tumors." (PMID 29958276, 2018).
colorectal cancer (9 papers, 2011 to 2024). A primary or metastatic malignant neoplasm that affects the colon or rectum. "By applying MC38, a colorectal cancer cell line, in a syngeneic mouse model of liver metastasis, Per1–/–Per2–/– mice had reduced liver metastasis, and Per2–/– livers had less cancer-associated fibroblasts infiltration and collagen deposition." (PMID 33816508, 2021). "As a circadian rhythm gene, PER1 has an important role in the cell cycle and affects the occurrence of cancer, including colorectal cancer." (PMID 34220965, 2021). "Interestingly, upregulation of Clock and CKIε expression was recently found in colorectal cancer tissues as compared to the adjacent normal mucosa and in these tissues the differential expression of Bmal1 and Per1 was correlated with metastasis." (PMID 24875049, 2014).
epilepsy (8 papers, 2015 to 2025). A brain disorder characterized by episodes of abnormally increased neuronal discharge resulting in transient episodes of sensory or motor neurological dysfunction, or psychic dysfunction. "In various animal models of epilepsy, the circadian oscillation and steady-state levels of circadian genes, including Bmal1, Clock, Per1, Rev-Erbα, and Rorα, have been found to be associated with epilepsy." (PMID 40217344, 2025). "Neuronal death in the hippocampus CA1 region in an experimental stroke model is enhanced in Per1 knockout mice, a factor that may contribute to the risk for developing epilepsy following cerebrovascular insults." (PMID 32714261, 2020). "In the rat pilocarpine model, epileptic and naïve rats were compared at specific ZT points following the development of spontaneous seizures, with results showing that development of epilepsy is associated with alterations in rhythmic changes of all three period genes (Per1, Per2, and Per3)." (PMID 32714261, 2020). "Various circadian genes such as Clock, Bmal1, Per1, Rev-erbα, and Rorα are involved in the regulation of epilepsy." (PMID 36013397, 2022). "Per1 is upregulated in the hippocampus following induction of experimental epilepsy, further evidence that seizures can perturb integral components of the clock." (PMID 32714261, 2020). "The rats with absence epilepsy (ie, GAERS) showed diurnal dysregulation of all core circadian clock genes, Per1, Cry1, Clock, and Bmal1, when compared to NECs, or had an epilepsy by time interaction where groups significantly varied depending on the time of day." (PMID 37805809, 2023). "Per1 up-regulation has also been seen upon depolarization in vitro or in epilepsy animal models, but its functional significance on epileptogenic process remains unclear." (PMID 30116220, 2018). "The PER gene family (PER1, PER2, and PER3) exhibits complex alterations in epilepsy models." (PMID 40940742, 2025). "Core clock genes including CLOCK, BMAL1, FBXL21, PER1, PER3, CRY1, and NR1D1 do not show evidence of harboring mutations that cause epilepsy in humans." (PMID 32714261, 2020). "Finally, we showed that temporal differences of sampling can change experimental results for Per1, Per3, Bmal1, Cry1 and Cry2, but not for Clock, which was consistently decreased in rats with epilepsy in all comparison to the naive group." (PMID 26473354, 2015).
hepatocellular carcinoma (8 papers, 2016 to 2024). A malignant tumor that arises from hepatocytes. "Per1/2 expression was also upregulated in fibroblasts and hepatoma cells treated with DEX and serum shock." (PMID 31388006, 2019). "However, Angptl8 shock in mouse Hepa1c1c-7 hepatoma cells for 2 h induced the expression of key clock regulators, whereas Per1 induction was the most significant compared to other factors." (PMID 31388006, 2019). "Moreover, the cAMP-CREB signaling pathway positively regulates Per1 expression in human hepatoma cells as well as the light-induced Per1 expression in the SCN." (PMID 30100984, 2018). "The impact of clock associated lncRNAs in hepatocellular carcinoma showed that the lncRNA HULC upregulates the expression levels of CLOCK and its downstream targets, like PER1 and CRY1 in hepatoma cells in vivo." (PMID 32344623, 2020).
Insulin resistance (7 papers, 2016 to 2025). Increased resistance towards insulin, that is, diminished effectiveness of insulin in reducing blood glucose levels. "Additionally, the expression levels of PER1, PER3, and BMAL1 molecular-clock genes in leukocytes obtained from patients with T2D was seen inversely correlated with hemoglobin A1C (HbA1c) levels, indicating an association between insulin resistance and T2D." (PMID 37475884, 2023). "At the level of q < 0.05, gene-based analysis detected significant associations of DNA methylation in four circadian genes (CLOCK, BMAL1, PER1, and PER2) with insulin resistance, fasting glucose, or HbA1c." (PMID 31031806, 2019). "In the liver, circadian mRNA and protein expression of clock genes such as PER1, PER2, BMAL1 and CLOCK and circadian-related metabolic regulators, such as AMPK, lipogenic enzymes, and gluconeogenic proteins are changed in response to HFD feeding, leading to obesity and insulin resistance." (PMID 36994336, 2021). "Furthermore, myeloid cell-specific PER1/2 disruption via bone morrow transplantation worsened HFD-induced liver inflammation, which was accompanied with increased severity of hepatic steatosis and insulin resistance." (PMID 36994336, 2021).
ovarian carcinoma (7 papers, 2016 to 2025). A malignant neoplasm originating from the surface ovarian epithelium. "In ovarian cancer, low PER1 expression is linked to reduced overall survival, particularly in early-stage (I+II) patients where low expression indicates poor prognosis." (PMID 41451215, 2025). "Studies have shown that PER1 expression in ovarian cancer is positively correlated with infiltration of neutrophils, Treg cells, and M2-type macrophages." (PMID 41451215, 2025). "In ovarian cancer, B lymphocyte, macrophage, and neutrophil infiltration levels were inversely correlated with PER1 gene expression." (PMID 38813085, 2024). "Previous study has shown that PER-1 is closely related to the stage and prognosis of ovarian cancer." (PMID 36118525, 2022). "Similarly, irradiated mice with genetic alterations on Per2 or Per1/2 genes accelerate salivary gland hyperplasia, teratomas, lymphoma, liver, and ovarian cancer, suggesting that Per genes act as tumor suppressor genes." (PMID 34361055, 2021). "However, the correlations of PER1 with prognosis and tumor-infiltrating lymphocytes in ovarian cancer (OV) remain unclear." (PMID 34220965, 2021). "We further evaluated the correlations between PER1 and these 10 interacting proteins based on the GEPIA database and found that the expression of PER1 in ovarian cancer was correlated with that of ARNTL, CLOCK, CRY1, CRY2, CSNK1D, CSNK1E, NPAS2, and PER3." (PMID 34220965, 2021).
Parkinson disease (7 papers, 2015 to 2025). A progressive degenerative disorder of the central nervous system characterized by loss of dopamine producing neurons in the substantia nigra and the presence of Lewy bodies in the substantia nigra and locus coeruleus. "Genetic variants of PER1 have been directly linked to Parkinson’s disease (PD), particularly in the pathogenesis of motor dysfunctions." (PMID 41451215, 2025). "Rs2253820 in PER1 (OR = 1.31, 95%CI: 1.17–1.48) was significantly associated with Parkinson’s disease risk in Han-nationality Chinese." (PMID 36672368, 2023). "In a Chinese population, BMAL1 rs900147 and PER1 rs2253820 SNPs were associated with Parkinson’s disease (PD)." (PMID 37761843, 2023). "In patients with Parkinson's disease (PD), the baseline levels of relative expression of the Bmal1 gene at approximately 9:00 am are found to be 57% lower than those of the Per1 gene in peripheral blood." (PMID 41243864, 2025).